COL4A3 (collagen type IV alpha 3 chain)
Description:
Type IV collagen is the major structural component of glomerular basement membranes (GBM), forming a 'chicken-wire' meshwork together with laminins, proteoglycans and entactin/nidogen. Tumstatin, a cleavage fragment corresponding to the collagen alpha 3(IV) NC1 domain, possesses both anti-angiogenic and anti-tumor cell activity; these two anti-tumor properties may be regulated via RGD-independent ITGB3-mediated mechanisms.
Synonyms: ATS2; ATS3; ATS3A; ATS3B; BFH2
Tractability: Small molecule: a structure with a bound ligand is known. Antibody: its Gene Ontology location is reachable by antibodies, with high confidence; UniProt places it where antibodies can reach, with medium confidence; UniProt predicts a signal peptide or a membrane-spanning region. PROTAC: ubiquitination databases record sites on it. Other modalities: an approved drug acts on it.
Gene: Protein-coding gene on chromosome 2 (227,164,624 to 227,314,792, forward strand). Ensembl gene ENSG00000169031.
Subcellular location: Secreted, extracellular space, extracellular matrix, basement membrane
Subcellular location (Human Protein Atlas): Vesicles; Endoplasmic reticulum; Predicted to be secreted
Pathways (Reactome):
Extracellular matrix organization: Anchoring fibril formation; Assembly of collagen fibrils and other multimeric structures; Collagen biosynthesis and modifying enzymes; Collagen chain trimerization; Collagen degradation; Crosslinking of collagen fibrils; ECM proteoglycans; Fibronectin matrix formation; Integrin cell surface interactions; Laminin interactions; Non-integrin membrane-ECM interactions
Developmental Biology: NCAM1 interactions
Disease: Attachment of bacteria to epithelial cells
Signal Transduction: Signaling by PDGF
Gene Ontology:
Molecular function: extracellular matrix structural constituent conferring tensile strength; integrin binding; protein binding; metalloendopeptidase inhibitor activity; structural molecule activity; extracellular matrix structural constituent
Biological process: endothelial cell apoptotic process; negative regulation of angiogenesis; negative regulation of vascular endothelial cell proliferation; cell surface receptor signaling pathway; collagen fibril organization; extracellular matrix organization; glomerular basement membrane development; negative regulation of cell population proliferation; sensory perception of sound
Cellular component: basement membrane; collagen type IV trimer; extracellular matrix; endoplasmic reticulum lumen; extracellular region; collagen trimer
Genetic constraint (gnomAD): Loss-of-function variants: 115 observed, 189.27 expected, observed/expected ratio (o/e) 0.61, 90% interval 0.52 to 0.71. The upper end of that interval is the gene's LOEUF score, 0.71, which puts it in group 2 of 6, group 1 being the genes least tolerant of losing a copy. Missense variants: 1,758 observed, 2,064.4 expected, observed/expected ratio (o/e) 0.85, 90% interval 0.82 to 0.89. Synonymous variants: 650 observed, 715.77 expected, observed/expected ratio (o/e) 0.91, 90% interval 0.85 to 0.97.
Gene-disease validity (ClinGen):
ClinGen rates the evidence that COL4A3 causes each of these diseases.
Alport syndrome (semidominant): Definitive. A rare renal disease characterized by glomerular nephropathy with hematuria progressing to end-stage renal disease (ESRD), frequently associated with sensorineural deafness, and occasionally with ocular anomalies.
Homologues: Orthologues: chimpanzee COL4A3 (99% identical), macaque COL4A3 (95% identical), pig COL4A3 (83% identical), dog COL4A3 (83% identical), mouse Col4a3 (79% identical), rat Col4a3 (77% identical), rabbit COL4A3 (75% identical). Paralogues in human: COL4A5 (54% identical), COL4A1 (52% identical), COL4A6 (46% identical), COL4A2 (45% identical), COL4A4 (38% identical), COL7A1 (36% identical), COL5A1 (34% identical), COL11A1 (34% identical), COL11A2 (32% identical), COL5A3 (32% identical), COL2A1 (32% identical), COL5A2 (31% identical), and 25 more.
Diseases named in the same sentence as COL4A3 in open-access papers:
COL4A3 is named in the same sentence as 164 diseases in open-access papers, as found by Europe PMC text mining. Sharing a sentence is not in itself a finding about the gene and the disease. The quoted sentences say what the papers report.
Alport syndrome (210 papers, 2009 to 2026). "We detected one likely pathogenic heterozygous in-frame variant in the COL4A3 gene associated with Alport syndrome in one patient originally diagnosed with primary GN." (PMID 41019761, 2025). "Alport syndrome is caused by variants in COL4A3, COL4A4, or COL4A5, which encode the α3α4α5 chains of type IV collagen." (PMID 41417821, 2025). "Alport syndrome involves chronic progressive kidney failure and extrarenal organ damage caused by COL4A3, COL4A4, and COL4A5 mutations." (PMID 39924725, 2025). "The COL4A5 gene resides on the X chromosome and causes X-linked Alport syndrome, while the COL4A3 and COL4A4 genes are both located on chromosome 2, resulting in an autosomal dominant or recessive mode of inheritance." (PMID 40004525, 2025). "The 3 disorders with the highest lifetime risk (>1.5 per 100,000), accounted for 24% of the overall lifetime risk and were caused by PKHD1 (autosomal recessive polycystic kidney disease), SLC12A3 (Gitelman syndrome), and COL4A3 (Alport syndrome) variants." (PMID 40677321, 2025). "The majority (57%) were located in the COL4A5 gene, reflecting the predominance of X-linked inheritance in Alport syndrome, while variants in the COL4A3 (19%) and COL4A4 (24%) genes accounted for autosomal forms of the disease." (PMID 40004525, 2025). "A well-described hereditary GBM disease is Alport syndrome, which is associated with a progressive glomerular disease, hearing loss, and lens defects due to genetic variants in the genes COL4A3, COL4A4, or COL4A5." (PMID 41299396, 2025). "Alport syndrome (AS) is a hereditary glomerulopathy caused by mutations in the COL4A3, COL4A4, or COL4A5 genes, leading to progressive kidney decline and extrarenal manifestations." (PMID 41243004, 2025). "COL4A3 is linked to an autosomal recessive form of Alport syndrome, characterized by kidney disease, sensorineural hearing loss, and sometimes, eye abnormalities, such as cataract." (PMID 40428427, 2025). "Inhibition of αvβ6 with a function-blocking monoclonal antibody attenuated renal fibrosis and inflammation in Col4a3-deficient Alport syndrome mice." (PMID 39990662, 2025). "Regarding the other mutated genes, as reported in the literature, the ones related to Alport syndrome (COL4A3, COL4A4) can be associated with kidney cysts." (PMID 39928271, 2025). "Alport syndrome is an inherited kidney disease that leads to end-stage kidney disease (ESKD) due to pathogenic variants in COL4A3/4/5, which encode type IV collagen." (PMID 41426028, 2025). "Alport syndrome (AS) is a hereditary glomerular disease caused by mutations in the COL4A3, COL4A4, and COL4A5 genes." (PMID 40406358, 2025). "Alport syndrome is caused by pathogenic variants in COL4A3, COL4A4, and COL4A5 genes encoding the α3, α4, and α5 chains of collagen type IV, respectively." (PMID 40392259, 2025). "Alport syndrome (AS) is a hereditary kidney disorder caused by mutations in COL4A3, COL4A4, and COL4A5, which often lead to progressive renal failure." (PMID 41290692, 2025). "Autosomal recessive Alport syndrome caused by disease-causing variants in COL4A3 and COL4A4 had a combined lifetime risk of 2.15 (1.64–2.79; European gnomAD), and 2.65 (2.24–3.12; worldwide gnomAD) per 100,000." (PMID 40677321, 2025). "A recent publication identified 12 genes, including the three genes associated with Alport syndrome (COL4A3, COL4A4, COL4A5), on a 274‐gene panel with the potential for carrier manifestations during pregnancy." (PMID 40317772, 2025). "The autosomal recessive form of Alport syndrome, caused by homozygous mutations in the COL4A3 or COL4A4 genes, accounts for fewer than 15% of cases." (PMID 41257164, 2025). "The most common form of digenic Alport syndrome involves pathogenic variants in both COL4A3 and COL4A4 genes, potentially resulting in a more severe clinical phenotype compared to individuals with a single variant." (PMID 40004525, 2025).
Alport syndrome (continued). "One had a likely pathogenic heterozygous variant in the COL4A3 gene associated with Alport syndrome, and one had a heterozygous novel variant of uncertain significance in the CD46 gene associated with atypical hemolytic uremic syndrome (aHUS)." (PMID 41019761, 2025). "We aimed to determine the frequency of variants in the Alport syndrome genes (COL4A3, COL4A4 or COL4A5) in individuals under 18 years of age presenting with persistent microscopic haematuria to a single specialist centre in the UK over a 10-year period." (PMID 39349776, 2025). "Specific Alport syndrome pathogenic variants in COL4A3 and COL4A4 can cause sub-clinical phenotypes in some patients, and severe manifestations of disease in others." (PMID 39883360, 2025). "The highest lifetime risk (> 1.5 per 100,000) was estimated for nephropathies caused by variants in PKHD1, SLC12A3, and COL4A3 associated with autosomal recessive polycystic kidney disease, Gitelman syndrome, and Alport syndrome, respectively." (PMID 40677321, 2025). "This study investigated genotype–phenotype correlations and the distribution of COL4A3/COL4A4 variants in a Lithuanian Alport syndrome cohort." (PMID 40806767, 2025). "Alport syndrome is a rare genetic disorder resulting from the mutations in the genes COL4A3, COL4A4, and COL4A5 that affect the synthesis, assembly, deposition, or function of the glomerular basement membrane." (PMID 40212398, 2025). "Genetically, Alport syndrome is caused by pathogenic variants in type IV collagen genes (COL4A3, COL4A4, and COL4A5), which lead to abnormalities in the glomerular basement membrane resulting in kidney dysfunction and progressive renal failure." (PMID 40852417, 2025). "Alport syndrome is caused by loss-of-function variants in one of the genes encoding the type IV collagen α3α4α5 network—COL4A3, COL4A4, or COL4A5." (PMID 41417821, 2025). "Among the probands with a clinical suspicion of Alport syndrome and detected changes, we revealed monoallelic variants in the COL4A3 or COL4A4 gene in 27% (29/109)." (PMID 40004525, 2025). "Loss of function mutations in the genes encoding these chains (Col4a3, Col4a4, and Col4a5) is associated with the loss of renal function observed in Alport syndrome (AS)." (PMID 38561223, 2024). "In patients with an a priori clinical diagnosis of glomerulopathy, pathogenic variants in COL4A5 or COL4A3 were detected in eight individuals, confirming the diagnosis of Alport syndrome." (PMID 39363361, 2024). "For the other forms of Alport syndrome, where variants are found in the COL4A3 or COL4A4 genes, there are different patterns of inheritance:1." (PMID 38745975, 2024). "The majority of genes clustered similarly in both datasets; for example, pLoF variants in COL4A3 (associated with Alport syndrome, MIM #104200) are uniformly distributed throughout the gene in both UKB and ClinVar." (PMID 38671509, 2024). "Alport Syndrome (AS) is the most common genetic glomerular disease, and it is caused by COL4A3, COL4A4, and COL4A5 pathogenic variants." (PMID 38790225, 2024). "Alport syndrome (AS), a hereditary kidney disease with a high risk for renal failure, is attributed to pathogenic variants in genes COL4A3, COL4A4, and COL4A5 that encode type IV collagen." (PMID 39071776, 2024). "Our results also show that loss of Col4a3 in endothelial cells is insufficient to generate the GBM defect associated with Alport syndrome, underscoring the critical role for podocytes in GBM type IV collagen production." (PMID 38561223, 2024). "Alport syndrome (AS) is a genetically heterogeneous disorder resulting from mutations in the collagen IV genes COL4A3, COL4A4, and COL4A5." (PMID 38433557, 2024). "Alport syndrome occurs at a prevalence of ~ 1% through mutations in COL4A3 (2q36.3), COL4A4 (2q36.3) or COL4A5 (Xq22.3)." (PMID 38668984, 2024).
Alport syndrome (continued). "AD Alport syndrome with heterozygous COL4A3 or COL4A4 variants typically results in haematuria, and sometimes FSGS but without a hearing loss or ocular abnormalities." (PMID 37578539, 2024). "Col4a2, Col4a3, and Col4a4 are associated with Alport's syndrome, a condition characterized by progressive hearing loss." (PMID 38413848, 2024). "The mutations in COL4A3/COL4A5 were implicated in the pathogenesis of Alport syndrome and thin basement membrane disease (TBMD)." (PMID 38202130, 2023). "Alport syndrome (AS) is caused by mutations in COL4A3, COL4A4 or COL4A5 genes, mainly pathophysicalological alterations affect the kidney, but the pathophysiology of AS is still not fully understood." (PMID 36968823, 2023). "Alport syndrome (AS) is a hereditary glomerulonephritis caused by COL4A3, COL4A4 or COL4A5 gene mutations and characterized by abnormalities of glomerular basement membranes (GBMs)." (PMID 37770589, 2023). "The case No. 5 of IHK has a compound heterozygous PKD1 genotype, involving a pathogenic and an uncertain significance variant, while the fetus is also heterozygous for a COL4A3 gene variant responsible of the autosomal dominant form of Alport syndrome." (PMID 37662847, 2023). "Alport syndrome is characterised by variants in the COL4A3, COLA4 and COL4A5 genes which code for type IV collagen α3-α4-α5 chains, respectively." (PMID 39429698, 2023). "A pathogenic variant in COL4A5 confirms the diagnosis of X-linked Alport syndrome, whereas variants in COL4A3 or COL4A4 confirm the diagnosis of Autosomal Dominant or Autosomal Recessive Alport Syndrome." (PMID 37895203, 2023). "Alport syndrome (AS) is the most common inherited glomerular disease caused by pathogenic variants of the COL4A3, COL4A4, or COL4A5 genes that encode type IV collagens." (PMID 36968823, 2023). "The most controversial is autosomal dominant Alport syndrome (ADAS) in patients with heterozygous mutation in COL4A4 or COL4A3 gene." (PMID 36982595, 2023). "Autosomal recessive Alport syndrome (ARAS) is caused by homozygous or compound heterozygous mutations in COL4A3 and COL4A4 genes." (PMID 36982595, 2023). "Mutation in one of the genes (COL4A3, A4, A5) encoding these proteins underlies the progressive genetic nephropathy Alport syndrome (AS) due to deficiency in trimerization and/or secretion of the α345(IV) trimer." (PMID 37143203, 2023). "Autosomal recessive inheritance caused by mutations in the COL4A3 or COL4A4 genes accounts for approximately 15% of Alport syndrome cases." (PMID 40625571, 2023). "Alport syndrome exhibits key clinical features such as hematuria, proteinuria, and a progressive decline in kidney function, attributed to genetic mutations in the COL4A3, COL4A4, and COL4A5 genes." (PMID 38235430, 2023). "In 2021, at the latest International Workshops on Alport Syndrome, the term AS spectrum disorder was accepted to refer to all disorders caused by variants in the COL4A3, COL4A4, or COL4A5 genes." (PMID 35880347, 2023). "Alport syndrome (AS) is a hereditary kidney disease caused by pathogenic variants in COL4A3 and COL4A4 genes with autosomal recessive or autosomal dominant transmission or in the COL4A5 gene with X-linked inheritance." (PMID 36982595, 2023). "Pathogenic variants in COL4A5 are responsible for the severe X-linked glomerulopathy, Alport syndrome (AS), while homozygous or compound heterozygous variants in the COL4A3 or the COL4A4 gene cause autosomal recessive AS." (PMID 37761826, 2023). "Of these, variants in COL4A3/4/5 (associated with Alport syndrome spectrum) comprised 31.8% of positive cases, and APOL1 high-risk genotypes comprised 45.5%." (PMID 37794564, 2023). "Alport syndrome (AS) is a rare disease characterized by defective glomerular basement membranes, caused by mutations in COL4A3, COL4A4, and COL4A5, which synthesize collagen type IV." (PMID 36936689, 2023).
Alport syndrome (continued). "Alport syndrome, caused by mutations in Col4a3, Col4a4 or Col4a5, causes progressive kidney dysfunction with proteinuria by injuring the GBM." (PMID 35271660, 2022). "This fact was in agreement with the wide range of features associated with heterozygous defects in COL4A3/4 in autosomal dominant forms of Alport syndrome." (PMID 36013122, 2022). "Alport syndrome is a hereditary kidney disease caused by mutations in the three genes encoding for collagen IV: COL4A3, COL4A4, and COL4A5." (PMID 36292778, 2022). "Individuals with AR Alport syndrome have two pathogenic variants in COL4A3 or COL4A4, and the COL4A3 and COL4A4 genes are affected equally often." (PMID 35602506, 2022). "We next wished to determine if col4a3- and col4a4-deficient zebrafish model had increased levels of proteinuria, which is a feature of Alport syndrome." (PMID 35716957, 2022). "Alport syndrome is inherited as an X-linked (XL), autosomal recessive (AR), or autosomal dominant (AD) disease, where pathogenic COL4A3 – COL4A5 variants affect the basement membrane collagen IV α3α4α5 network." (PMID 35602506, 2022). "One such condition is Alport syndrome, which is caused by variants in COL4A3, COL4A4 or COL4A5 in humans." (PMID 35716957, 2022). "Patients with isolated microscopic hematuria and heterozygous variants in COL4A3 or COL4A4 are considered to have autosomal dominant Alport syndrome (ADAS), which therefore eliminates the diagnosis of thin basement membrane nephropathy (TBMN)." (PMID 35547199, 2022). "Alport syndrome is a genetically heterogenous Type IV collagenopathy linked to the COL4A3, COL4A4, and COL4A5 genes." (PMID 35760791, 2022). "Alport syndrome is the commonest genetic kidney disease and results from pathogenic variants in COL4A3, COL4A4 or COL4A51,2." (PMID 35789182, 2022). "Autosomal dominant (AD) Alport syndrome is caused by a heterozygous pathogenic variant in COL4A3 or COL4A4 and associated with isolated haematuria and a thinned rather than lamellated membrane." (PMID 35602506, 2022). "Alport syndrome results from a myriad of variants in the COL4A3, COL4A4, or COL4A5 genes that encode type IV (basement membrane) collagens." (PMID 35223933, 2022). "Alport syndrome is a hereditary disorder characterized by renal impairment, hearing loss, and ocular symptoms and is caused by COL4A3, COL4A4, and COL4A5 mutations." (PMID 36045115, 2022). "In this study, we provide the relevant data on disease prognosis in autosomal dominant forms of Alport syndrome in a large cohort of 317 cases including two novel deleterious missense mutations in COL4A3, described in this report." (PMID 36013122, 2022). "Autosomal recessive Alport syndrome (ARAS) is caused by homozygous or compound heterozygous mutations in COL4A3 and COL4A4 genes and accounts for ~5% of patients with AS." (PMID 35547199, 2022). "Autosomal dominant Alport syndrome, formerly known as ‘thin basement membrane nephropathy’, results from heterozygous pathogenic variants in COL4A3 or COL4A410." (PMID 35789182, 2022). "The COL4A3/COL4A4 heterozygous variants were also reported to cause autosomal dominant Alport syndrome (ADAS, OMIM 104200), while homozygous or compound heterozygous variants were responsible for the autosomal recessive Alport syndrome (ARAS)." (PMID 36699462, 2022). "Recent reports demonstrate that pathogenic variants in COL4A3/A4/A5 account for a significant and unappreciated proportion of patients with Alport syndrome in CKD." (PMID 33851121, 2021). "Alport syndrome is a hereditary glomerular disease caused by mutation in the COL4A3, A4, or A5 gene encoding type IV collagen α3–5 (α3–5(IV)) chains, which are components of the glomerular basement membrane." (PMID 33782421, 2021). "Alport syndrome (AS) is a hereditary glomerular nephritis caused by mutation in one of the type IV collagen genes α3/α4/α5 that encode the heterotrimer COL4A3/4/5." (PMID 33706638, 2021).